NLRP3 (NLR family pyrin domain containing 3)
Diseases named in the same sentence as NLRP3 in open-access papers (continued):
Sharing a sentence is not in itself a finding about the gene and the disease.
interstitial cystitis (7 papers, 2022 to 2025). A rare chronic debilitating urogenital disease characterized by urinary frequency, urgency, and pelvic pain. "MSC-Exos have been shown to modulate NLRP3 inflammasome activity and attenuate spinal neuroinflammation in interstitial cystitis by inhibiting NLRP3 inflammasome activation and downregulating TLR4/NF-κB signaling pathway activity." (PMID 40433382, 2025). "This work was carried out under the project entitled “Mechanisms of exosomes derived from HUC‐MSCs enriched with miR‐9 regulating the activity of NLRP3 inflammasome through TLR4 in the treatment of bladder pain of interstitial cystitis/bladder pain syndrome”." (PMID 38415918, 2024). "Towards, an herbal medicine-derived Shionone alleviates interstitial cystitis in rat model via NF-κB, NLRP3 and GSDMD-N mediated pathways." (PMID 35720309, 2022).
Listeria infection (7 papers, 2010 to 2026). "This protein showed ASC speck induction upon Listeria infection but also responded to nigericin and imiquimod treatment as observed with NLRP3 wild-type." (PMID 41266655, 2026). "Only at lower, more physiological doses [MOI (multiplicity of infection) 30 to 40], Listeria infection activated the NLRP3/caspase-1 pathway and the processed caspase-1 p20 product became evident by immunoblotting." (PMID 40053580, 2025). "Recently, an increase in transcriptional levels of inflammatory factors was demonstrated, where levels of proteins associated with NLRP3, NF-κB and ERK were increased after Listeria infection and consequent inflammation of the central nervous system." (PMID 36761775, 2023). "In the case of Salmonella and Listeria infections, necrosis induction requires the caspase-1-mediated inflammasome of NLRP3, although the cascade of events downstream of caspase-1 that are responsible for cell death remains unknown." (PMID 21740493, 2011). "To identify which domains within NLRP6 sense Listeria infection, we created a set of chimeras between NLRP6 and NLRP3, using corresponding domains in NLRP3 as place holders to generate functional receptors." (PMID 41266655, 2026).
metastatic melanoma (7 papers, 2016 to 2024). A melanoma that has spread from its primary site to another anatomic site. "We show the formation of the NLRP3 inflammasome in biopsies of metastatic melanoma using fluorescent resonance energy transfer analysis for NLRP3 and apoptosis-associated speck-like protein containing a CARD." (PMID 33649199, 2021). "Cultured human metastatic melanoma 1205Lu cells exhibit a time-dependent spontaneous release of IL-1β, which was reduced with NLRP3 silencing using small-interfering RNA (siRNA)." (PMID 33649199, 2021). "The nucleotide-binding domain, leucine-rich containing family, pyrin domain-containing-3 (NLRP3) inflammasome, an intracellular complex that regulates maturation and release of interleukin (IL)-1β, is active in biopsies of metastatic melanoma." (PMID 33649199, 2021). "Consistently, another study reported that NLRP3 downregulation and reduced IL-1β secretion decreased metastatic melanoma by thymoquinone therapy in a mouse model." (PMID 34747716, 2021). "It has been shown that NLRP3 downregulation and reduced IL-1β secretion decreased metastatic melanoma by thymoquinone therapy in a mouse model." (PMID 34747716, 2021). "In addition, we curated 336 advanced/metastatic melanoma patients treated with ICI agents from 6 published studies to analyze the response rate and survival outcome in relation to NLRP3 mutations." (PMID 34747716, 2021). "Alternatively, we observed NLRP3 activation in B16F10 metastatic melanoma independent of anti-PD-1 therapy." (PMID 34531850, 2021).
Miscarriage (7 papers, 2018 to 2025). A pregnancy that ends at a stage in which the fetus is incapable of surviving on its own, defined as the spontaneous loss of a fetus before the 22th week of pregnancy. "Collectively, these findings indicate that ML345 efficiently ameliorates LPS-induced miscarriage by restraining NLRP3 inflammasome activation and associated inflammatory responses." (PMID 41231359, 2025). "This is supported by the moderately strong association between the NLRP3 inflammasome concentration and Ca in women with spontaneous miscarriage and in the “NET-negative” group." (PMID 39408839, 2024). "The aim of the conducted research was to evaluate the involvement of the NLRP3 inflammasome as a potential causative factor in the pathogenesis of spontaneous miscarriages." (PMID 39408839, 2024). "In this study, ML345 ameliorated LPS-induced miscarriage by inhibiting NLRP3 inflammasome activation." (PMID 41231359, 2025). "Statistically significant higher concentrations of NLRP3 and IL-18 were found in the sera of all women with miscarriage as compared to the values obtained in the control group." (PMID 39408839, 2024). "Significantly higher concentrations of NLRP3 and IL-18 were demonstrated in the serum of patients with miscarriage as compared to the control group." (PMID 39408839, 2024). "The concentrations of NLRP3, IL-1β, IL-18, and cytochrome C in the serum of patients after miscarriage were measured by means of the immunoenzymatic method." (PMID 39408839, 2024). "Our findings represent a new concept regarding the role of extracellular vesicles, miR-138-5p, GPR124, and the NLRP3 inflammasome in normal early pregnancy and spontaneous miscarriage." (PMID 35745744, 2022). "Furthermore, increased m6A methylation on NLRP3 mRNA mediated by METTL3 can enhance the interaction between Z-DNA-binding protein 1 (ZBP1) and NLRP3 proteins, promoting trophoblast cell apoptosis and leading to miscarriage." (PMID 40001550, 2025). "Furthermore, ML345 demonstrated robust in vivo efficacy while being well tolerated, mitigating diverse NLRP3-driven pathologies, including systemic inflammation and miscarriage triggered by LPS." (PMID 41231359, 2025). "Additionally, in the group of women with diagnosed spontaneous miscarriage, we found a similar statistical relationship between NLRP3 and Na." (PMID 39408839, 2024). "In contrast, GRP124 with siRNA invalidated the GRP124-regulated expression of NLRP3, IL-18, and IL-1β in human decidual endometrial stromal cells, indicating that the effects of GRP124 on spontaneous miscarriage are through the expression of inflammasome NLRP3, IL-18, and IL-1β." (PMID 35745744, 2022). "In aggregate, attempts to manipulate the GPR124 and inflammasome NLRP3, IL-18, and IL-1β signaling that have a critical role in spontaneous miscarriage may be a way to clarify the actions of mi138-5p in decidual endometrial stromal cells related to embryo implantation and early pregnancy." (PMID 35745744, 2022). "Although NLRP3 expression is upregulated in miscarriage, its therapeutic relevance has not been fully established." (PMID 41231359, 2025). "Only 10% of the placental tissue samples from women with miscarriage showed a weak expression of NLRP3 and Fas, with no detection of these proteins in the control samples." (PMID 39408839, 2024). "We demonstrated the excessive activation of inflammasome NLRP3, IL-18, and IL-1β in spontaneous miscarriage compared to normal pregnancy." (PMID 35745744, 2022). "In the miscarriage model, ML345 not only decreased IL-1β levels but also reduced IL-6 and TNF, which are independent of NLRP3." (PMID 41231359, 2025).
myeloid leukemia (7 papers, 2020 to 2025). A clonal proliferation of myeloid cells and their precursors in the bone marrow, peripheral blood, and spleen. "krasG12D-induced NLRP3 activation is dependent on RAC1-mediated accumulation of ROS in myeloid leukemia cells." (PMID 37081882, 2023). "In agreement with our observations in mice, patient-derived myeloid leukemia cells exhibit KRAS/RAC1/ROS/NLRP3/IL-1β axis activity." (PMID 32246016, 2020). "This work revealed the existence of KRAS/RAC1/ROS/NLRP3/IL-1β pathway in human myeloid leukemia." (PMID 37081882, 2023). "Furthermore, 1,2-diol can also suppress the NLRP3 inflammasome in human myeloid leukemia mononuclear cells (THP-1) cell lines." (PMID 35222388, 2022). "The results showed that 4-benzene-indol derivative could not only suppress the activation of NLRP3 inflammasome both in vitro and alleviate LPS-induced ALI in vivo but also suppress the NLRP3 inflammasome in human myeloid leukemia mononuclear cells (THP-1) cell lines." (PMID 35222388, 2022). "Human myeloid leukemia mononuclear (THP-1) cells and mouse peritoneal macrophages (MPMs) were stimulated with lipopolysaccharides (LPS) and Nigericin to activate NLRP3 inflammasomes, which simulated an inflammation environment in vitro." (PMID 34294138, 2021). "The results showed that 1,2-diol could not only suppress the activation of NLRP3 inflammasome both in vitro and alleviate LPS-induced ALI in vivo, but also suppress the NLRP3 inflammasome in human myeloid leukemia mononuclear cells (THP-1) cell lines." (PMID 35222388, 2022).
Neonatal onset (7 papers, 2013 to 2025). Onset of signs or symptoms of disease within the first 28 days of life. "A number of these mutations (D303H, K568N, and Y570C) are known to cause the severe NLRP3-AID neonatal-onset multisystem inflammatory disease (Infevers Database) and include several somatic mutations (D303H, K565E, E567G, K568N, and Y570C)." (PMID 40892070, 2025). "In addition, the gain-of-function mutations in NLRP3 have been identified as the cause of the inherited cryopyrin-associated periodic syndrome Muckle–Wells syndrome, familial cold autoinflammatory syndrome, and neonatal-onset multisystem inflammatory disease." (PMID 29163487, 2017).
pneumoconiosis (7 papers, 2015 to 2023). An occupational lung disorder caused by inhalation of dust particles. "The association between the NLRP3 rs1539019 polymorphism and HCV infection is in the same line with a study demonstrating a strong association between the NLRP3 rs1539019 polymorphism and pneumoconiosis in Chinese coal workers." (PMID 30728751, 2019).
primary biliary cholangitis (7 papers, 2020 to 2024). Primary biliary cholangitis (PBC) is a chronic and slowly progressive cholestatic liver disease of autoimmune etiology characterized by injury of the intrahepatic bile ducts that may eventually lead to liver failure. "Specific binding of Gal-3 to NLRP3 and inflammasome activation were shown in a mice model of primary biliary cholangitis." (PMID 38711500, 2024). "The role of Galectin-3 in the specific binding to NLRP3, and inflammasome activation in models of primary biliary cholangitis has been recently described." (PMID 32707678, 2020). "In this study, it has been reported that in primary biliary cholangitis (PBC), the NLRP3 inflammasome process plays a crucial role in guiding macrophage activation through in vitro and in vivo experiments." (PMID 37509299, 2023). "There is evidence that the NLRP3 inflammasome and its downstream effectors are upregulated in cholestatic diseases in humans, e.g., biliary atresia, primary biliary cholangitis (PBC) and primary sclerosing cholangitis (PSC)." (PMID 34685598, 2021). "An examination of livers in patients with Primary Biliary Cholangitis (PBC) revealed Gal-3’s increased expression and NLRP3 activation to be Gal-3 dependent." (PMID 38172822, 2024). "In Novosphingobium aromaticivorans-induced primary biliary cholangitis (PBC), Galectin-3 was found to enhance NLRP3 inflammasome activation, thereby stimulating IL-1β production and worsening the progression of PBC." (PMID 37685870, 2023). "Furthermore, despite recent clinical research demonstrating inter-relationships of Gal-3 and NLRP3 inflammasome with primary biliary cholangitis (PBC) and inflammatory bowel disease, no studies to date have investigated such inter-relationships in OLP." (PMID 38172822, 2024).
retinal (7 papers, 2015 to 2025). "In this study, we are the first to identify ZLHXTY alleviates retinal neurodegeneration and vascular injury by inhibited pyroptosis via mediating NLRP3 inflammasome activation in HR mice." (PMID 40469974, 2025). "We therefore initially compared MCMV-infected eyes of groups of retinitis-resistant MAIDS-4 mice with the MCMV-infected eyes of groups of retinitis-susceptible MAIDS-10 mice for detection and quantification of NLRP3, NLRP1b, or AIM2 transcripts." (PMID 41011779, 2025). "Five kinds of retinal lesions were seen in 5 patients (10 eyes, 25%) with NLRP3-AID, including peripheral retinal vascular leakage, microaneurysms, macular ischemia, macular epiretinal membrane formation and drusen." (PMID 37480029, 2023). "Previously, we have shown that tonabersat can decrease retinal inflammation by targeting the NLRP3 inflammasome pathway in RPE cells exposed to high glucose and pro-inflammatory cytokines." (PMID 36835288, 2023). "The NLRP3+ F4/80+ macrophages detected in the subretinal space of WTanimals were distributed at the focal retinal lesion and towards the lesion edges, with the rounded amoeboid morphology of activated macrophages." (PMID 30126455, 2018). "HMGB1 led to the activation of canonical NLRP3 and non-canonical caspase-8 inflammasomes and the processing of IL-1β in retinal IR injury." (PMID 26224068, 2015). "The protein expression of NLRP3 or ASC was not significantly changed at 8 h and 16 h after retinal IR injury in either caspase-11−/− mice or WT mice." (PMID 39333859, 2024). "However, the protein expressions of NLRP3 and ASC did not significantly change after retinal IR injury." (PMID 39333859, 2024).
retinal degeneration (7 papers, 2016 to 2025). Degeneration of the retina. "Substantial evidence in the literature suggests the activation of NLRP3 inflammasome in retinal degeneration through a significant augmentation in the inflammasome components, including NLRP3, ASC, and CASP1." (PMID 35008812, 2021). "In addition, we showed that the use of antibodies against TNFα ameliorated retinal degeneration and downregulated NLRP3 inflammasome components." (PMID 36670960, 2022). "We reasoned that inflammasome mediated-inflammation in retinal degenerations such as AMD may occur largely independently of NLRP3, NLRC4 or AIM2 sensor proteins." (PMID 32041990, 2020). "However, our work indicated that, during the BLE-induced retinal degeneration, the NLRP3 inflammasome and the following IL-1β were mainly expressed in activated microglia." (PMID 27831552, 2016). "NLRP3 is the best characterised CASP-1-dependent inflammasome sensor protein, and although widely studied, its role in the progression of retinal degenerations such as AMD has yet to be fully elucidated." (PMID 32041990, 2020). "In addition to NLRP3, the role of alternative CASP-1-dependent inflammasome components in retinal degenerations was also investigated." (PMID 32041990, 2020). "Finally, in addition to investigations into NLRP3, the role of NLRC4 and AIM2 inflammasome sensor proteins in retinal degenerations was examined." (PMID 32041990, 2020).
sensorineural hearing loss (7 papers, 2021 to 2026). "The NLRP3 inflammasome, a key component of the innate immune system, has emerged as a central mediator of inflammation-driven sensorineural hearing loss (SNHL)." (PMID 41046290, 2025). "Cochlear autoinflammation and activation of NLRP3 inflammasome in vestibular-resident macrophage-like cells seems to be a common mechanism leading to chronic inflammation, in both sensorineural hearing loss and MD." (PMID 38396174, 2024).
sickle cell anemia (7 papers, 2022 to 2026). "The platelet nucleotide-binding domain leucine-rich repeat-containing protein 3 (NLRP3) inflammasome is upregulated in sickle cell disease (SCD) and promotes platelet aggregation." (PMID 41643555, 2026). "Apart from pain, continuous lysis of fragile sickled erythrocytes leads to the release of heme, which is a strong activator of the NLRP3 inflammasome, thus producing chronic inflammation in sickle cell disease." (PMID 37180702, 2023). "Considering the potent role of flurbiprofen in inhibiting NLRP3 inflammasome and other inflammatory cytokines in sickle cell disease, our data suggests that it can be explored further for better sickle cell disease pain management along with the possibility of disease modification." (PMID 37180702, 2023). "However, with a focus of sickle cell disease, we screened these drugs against heme-induced NLRP3 inflammasome in THP-1 cells." (PMID 37180702, 2023). "Notably, NLRP3 cooperates with Bruton's tyrosine kinase (BTK) to amplify platelet aggregation and thrombosis, particularly in diseases like sickle cell anemia (SCD), where HMGB1/TLR4-NLRP3/BTK crosstalk exacerbates thrombosis." (PMID 40520933, 2025).
small cell lung carcinoma (7 papers, 2018 to 2025). Small cell lung cancer (SCLC) is a highly aggressive malignant neoplasm, accounting for 10-15% of lung cancer cases, characterized byrapid growth, and early metastasis. "RRx-001 is a minimally toxic NLRP3 inhibitor in Phase 3 for small cell lung cancer (SCLC) that is associated with vascular normalization properties as well as epigenetic inhibition and tumor associated macrophage repolarization through CD47 downregulation." (PMID 36960054, 2023). "Among these structurally different small molecules, the most clinically advanced, which directly targets the NLRP3 pathway is RRx-001 that has now entered phase III study in patients with small cell lung cancer (SCLC)." (PMID 39653810, 2025). "As an example, RRx-001 is expected to be evaluated for several different indications: 1) small cell lung cancer (SCLC) 2) mucositis 3) radiation countermeasure 4) leukemia and myelodysplastic syndrome 5) NLRP3 inflammasome-related diseases." (PMID 36635930, 2023). "Consistent with previous findings, we found that MCC950, a specific small-molecule inhibitor of NLRP3, could significantly inhibit the proliferation of both small cell lung cancer (SCLC) and non-SCLC cells." (PMID 36694200, 2023). "Our results showed distinct NLRP3/Caspase 1 dependent IL-1β maturation in alveolar macrophages relative to peripheral blood cells with strong stimulation in the periphery and reduced stimulation locally in the lungs of NSCLC and small cell lung cancer (SCLC) groups." (PMID 30365491, 2018).
transient cerebral ischemia (7 papers, 2017 to 2024). "Another Swedish study showed that genetic variants in NLRP3 were associated with the risk of transient ischemic attack (TIA) or stroke in RA patients." (PMID 35095918, 2021). "AS-IV has been reported to has neuroprotective effects against transient cerebral ischemia through the suppression of NLRP3 inflammasome activation." (PMID 31558153, 2019). "Astragaloside IV might exert anti-inflammatory effects by inhibiting toll-like receptor 4 (TLR4) signaling pathway and nucleotide binding oligomerization domain-like receptors P3 (NLRP3) inflammasome overactivation in order to prevent transient cerebral ischemia and reperfusion injury." (PMID 29358972, 2017).